CDKN2A (cyclin dependent kinase inhibitor 2A)
Diseases named in the same sentence as CDKN2A in open-access papers (continued):
Sharing a sentence is not in itself a finding about the gene and the disease.
tumor (continued). "The largest study was a pan-tumor study of CDKN2A and MTAP expression as a surrogate for 9p21.3 heterozygous or homozygous deletion, which confirmed our earlier HNSC/TME findings, specifically showing that 9p21.3 loss in HPV– HNSC was associated with immune-cold, CD8 T-cell depleted TME." (PMID 36395141, 2022). "Together, these data revealed common features of GBM, including gain of chr.7 and loss of chr.10, lacking IDH1/2 mutations, high frequency of TERT promoter mutation, loss of critical tumor suppressors (e.g., PTEN and CDKN2A/CDKN2B), high frequency of PDGFA and EGFR amplification." (PMID 34987659, 2022). "In an analysis of immune cell infiltration, high CDKN2A expression was positively and significantly associated with many activated immune cells, which indicated that CDKN2A may be involved in tumor immunity." (PMID 35004697, 2021). "Relative to tumor tissues, the expression level of CDKN2A was lower in adjacent normal specimens." (PMID 35004299, 2021). "Interestingly, although the breakpoints for these losses are different in each tumor, they all occur in a narrowed region around CDKN2A/2B genes, and for three tumors the breaks occurred in the MLLT3 gene." (PMID 33963205, 2021). "Interestingly, NSCLC patients with IFN I and CDKN2A gene HDs have a significantly worst disease free survival than patients with only CDKN2A gene HD, suggesting a tumor suppressor role for IFN I genes in this cancer." (PMID 34249754, 2021). "Moreover, the tumor suppressor locus cyclin-dependent kinase inhibitor 2A/B can affect pigmentation phenotypes in the chicken." (PMID 33995468, 2021). "Furthermore, CDKN2A expression was significantly higher in 15 tumors, which was consistent with tumor stage analysis in COAD, KIRC, KIRP, KIHC, LIHC and THCA." (PMID 35004697, 2021). "CDKN2A gene methylation has been reported in 23–67% of primary OSCC tumours." (PMID 34041255, 2021). "CDKN2A could inhibit the tumor-promoting behavior of CDK4/6, and given that the CDKN2A alteration is frequent in HCC, CDK4/6 inhibitors are presently being tested in advanced HCC." (PMID 33407585, 2021). "Pre-clinically, this combination is particularly efficacious against CT26 colon carcinoma cells, which interestingly harbor a Cdkn2a deletion and expresses functional RB, likely rendering it highly sensitive to the tumor-intrinsic immunomodulatory effects of CDK4/6 inhibition." (PMID 34025662, 2021). "We also observed copy number gains in EZH2 (chr7:148,504,464–148,581,441), PTEN (with LOH, chr10:89,622,870–89,731,687), and EED (chr11:85,955,806–85,989,785) in both the cell line and tumor Like NF1, the tumor suppressor CDKN2A is frequently mutated in NF1-associated MPNSTs." (PMID 33707600, 2021). "The expression of CDKN2A was highly variable across different normal tissues and tumor tissues." (PMID 34405225, 2021). "Given the predicted CDKN2A activation in one of the subclusters but the inability to perform immunofluorescence assays in tumor samples, we cannot predict whether p16(INK4A), and/or p14(ARF) are upregulated in this subcluster." (PMID 34003213, 2021). "The tumor marker CDKN2A had the highest fold change in CIN3/AIS as compared to normal biopsies." (PMID 35008799, 2021). "However, fluorescent in situ hybridization (FISH) on MPM tumor tissues has revealed that the CDKN2A homozygous deletion cannot be detected in all cells." (PMID 34277422, 2021). "In mice, CDKN2A knockout enhances UV-induced tumor formation." (PMID 34553848, 2021). "However, CDKN2A expression is associated with infiltrating lymphocyte (TIL) levels, suggested that CDKN2A expression is related with tumor immunity." (PMID 35004697, 2021). "9p21.3 and is often co-deleted with CDKN2A, a frequently deleted tumor suppressor in human cancers." (PMID 34234122, 2021).
tumor (continued). "The high expression of CDKN2A can promote the proliferation of cancer cells, inhibit the apoptosis of cancer cells, induce tumor interstitial angiogenesis, reduce the sensitivity of cancer cells to chemoradiotherapy, and ultimately affect the prognosis of HCC patients." (PMID 34405225, 2021). "Transcription factors like NOTCH1 (16%) and KMT2B (16%), UNC13C (14%), another tumor suppressor, ERCC2 (14%) involved in nucleotide excision repair pathway, were recurrently mutated, whereas genes like CDKN2A, MLH1, FGFR1, EGFR, etc. had a less than 10% mutation frequency." (PMID 34796107, 2021). "Hence, these data suggest an evolutionary model where loss of whole chromosome 9 is selected as a driver event early in tumor evolution (e.g., due to CDKN2A), but then later leads to collateral sensitivity to immunotherapy, possibly due to 9q34 (TRAF2) loss." (PMID 33508232, 2021). "Furthermore, some oncogenic genes like EGFR, CDK6, YAP1, and MMP7 were amplified in the TP53INP2-low patients while some tumor suppressor genes including CDKN2A, KLF6, and PTEN were deleted." (PMID 33897760, 2021). "The expression level of the CDKN2A gene was higher in tumor tissue than in normal tissue." (PMID 35004697, 2021). "CDKN2A silencing due to DNA methylation promotes cell proliferation and tumour development." (PMID 34041255, 2021). "CDKN2A/2B is an important tumour suppressor gene, belonging to the CDK inhibitor gene family." (PMID 34418317, 2021). "The most frequent in MPM pathogenesis are genetic mutations in tumor suppressor genes (including neurofibromin 2 (NF2, merlin), cyclin-dependent kinase inhibitor 2A (CDKN2A), which shares a locus for both p16/INK4 and p14/ARF, and BRCA-associated protein-1 (BAP-1)." (PMID 34361048, 2021). "This choice is justified by the following: (i) the role of class IIa and of their partners in this tumor is well characterized and (ii) mutations in two key elements of the senescent pathway, RB1 and CDKN2A, in LMS are mutually exclusive and strongly associate with patient survival." (PMID 33966634, 2021). "ΔNp63α represses CDKN2A, which produces the two tumor suppressors, p16 (p16INK4a) and p14 (p14Arf)." (PMID 34553848, 2021). "Notably, the data gained supported the fact both hypermethylation and hypomethylation of the CDKN2A gene region played a vital role in tumor genesis by regulating classic cancer-related signaling pathways." (PMID 33896386, 2021). "We therefore studied the prognostic value of CDKN2A/B in our classified tumor cohort (n = 123)." (PMID 33941250, 2021). "In particular, the frequency of CDKN2A LOF increased with more advanced tumor stage in all three cohorts (CDKN2A LOF incidence in early stage vs. advanced stage cohort 1 [N = 1144]: 28% vs. 35% p = 0.016; cohort 2 [N = 586]: 16% vs. 25% p = 0.015; cohort 3 [N = 183]: 12% vs. 28% p = 0.11)." (PMID 34625620, 2021). "The patient’s tumor harbored a sole alteration in CDKN2A/B and demonstrated a response with single-agent palbociclib (30% regression; partial response by RECIST 1.1; tumor marker, CA 125, 328 [baseline] down to 50 U/ml [reference range, 0–34 U/ml], PFS, 8.0 months)." (PMID 33427211, 2021).
tumor (continued). "Overall, these results suggest that, although aberrations of BAP1, CDKN2A, and other tumor suppressor genes are the commonest genomic cancer-driving hits in MM, some rare cases of MM might also be driven by genomic dysregulation of MET signaling." (PMID 34884673, 2021). "Moreover, the correlation between the expression of CDKN2A and immune cell marker genes suggests the role of CDKN2A in regulating tumor immunology of HCC." (PMID 34405225, 2021). "However, all homozygous deletions were clonal and shared by paired tumor samples, and, as expected, often located in the CDKN2A locus." (PMID 34261524, 2021). "This study further strengthens the evidence for the function of CDKN2A in tumor suppression." (PMID 34572732, 2021). "However, despite the heterozygous CDKN2A P16WT/G101W/P14WT/R115L germline variant, cell cycle checkpoints were still activated upon KRASG12Dexpression, posing a potentially relevant tumor progression barrier." (PMID 34680288, 2021). "However, the correlation between the tumor CDKN2A mRNA expression level, p16-positive cell percentage and p16 immunohistochemistry H-score was only moderate." (PMID 34948172, 2021). "That NSCLC tumor actively targets the CDKN2a/p16 locus rather than the observed mutational enrichment in this locus due to a selection process during lung carcinogenesis and tumor progression." (PMID 34395246, 2021). "Patients verified with a complete loss (CNV = 0) of CDKN2A, a well-known tumor suppressor, lacked detectable protein amounts." (PMID 33722259, 2021). "In HCC, the abnormalities in CDKN2A gene and cell cycle pathway could promote cell proliferation and tumor growth." (PMID 34331411, 2021). "In these tumors, CDKN2A may be a potential immunotherapeutic biomarker to affect tumor cell viability." (PMID 35004697, 2021). "The CDKN2A deletions detected in 2XSB cells was also present in the parent tumor." (PMID 33707600, 2021). "Homozygous deletion of CDKN2A/B was neither significantly associated with patient age or sex nor with the tumor location." (PMID 32642869, 2020). "Finally, we assessed the potential impact of incorporating CDKN2A status into tumor grading criteria in our institutional cohort." (PMID 33081848, 2020). "In our analyses, the chromosomal region 9p21.3-p21.1, including the gene CDKN2A, was different in tumor tissue (1x clonal loss; 1x no aberration) and cell subpopulations (loss)." (PMID 32634135, 2020). "Multivariate Cox Proportional-Hazards analysis demonstrated that histologic grade and CDKN2A status are independent predictors of survival, and the prognostic value of CDKN2A is maximized by applying a threshold of ≥ 30% of tumor cells with homozygous deletion by FISH to define a positive result." (PMID 33081848, 2020). "With the exception of tumor 2, all tumor samples showed characteristic mutations of HNSCC including amplification of 3q26.2 (TP63, SOX2, PIK3CA), 5q14.3 (APC), 8q24.3 (PTK2), 8q22.3 (LRP12) as well as loss and/or LOH of 9p21.3 (CDKN2A)." (PMID 32426287, 2020). "The choice of where to set the clinical cutoff for defining tumor wide CDKN2A deletion based on the proportion of tumor cells with homozygous deletion will be critically important if CDKN2A status is to be used for tumor grading and therapeutic decision-making." (PMID 33081848, 2020). "Moreover, 16 of the top 20 CIS genes had supporting fusion transcripts from at least one tumor, including Cdkn2a, Nf1, Pten, Sox6, Sox5, Spred1, and Tcf12 (all containing PB splice acceptor fusions, implying transcript termination)." (PMID 32727536, 2020). "Here we report in two different cancers sensitive to T cell-mediated rejection, that deletion of the senescence-inducing cell cycle regulators p16Ink4a/p19Arf (Cdkn2a) or p21Cip1 (Cdkn1a) in the tumour cells abrogates both the natural and the ICB-induced cancer immune control." (PMID 32165639, 2020).
tumor (continued). "p16INK4a (CDKN2A) is a central tumor suppressor, which induces cell-cycle arrest and senescence." (PMID 32483135, 2020). "Additionally, there is emerging pre-clinical and clinical data explaining potential mechanisms by which CDKN2A deletions, perhaps in combination with other concurrent genetic aberrations, contribute to tumor progression in pediatric LGGs." (PMID 33153497, 2020). "Other mutated tumor suppressors were KEAP1 (17%), RB1 (4%), and CDKN2A (4%)." (PMID 32257951, 2020). "There are several studies demonstrated that methylation or ANRIL regulation may downregulate CDKN2A/B and its downstream tumor suppressors (p14ARF and p16INK4A), resulting in tumor formation and progression." (PMID 33122978, 2020). "In addition to an MDM2 amplification, copy number analyses also revealed amplification of CDK4 in three tumors (cases 1–3) and a deletion of CDKN2A in one tumor (case 5)." (PMID 32352245, 2020). "We did not observe a significant difference in tumor incidence or latency between experimental groups with and without additional Cdkn2a loss (sgCdkn2a versus sgControl)." (PMID 33228790, 2020). "Hepatitis viral infection causes a high level of ROS-induced DNA base damage, increasing the DNA methylation at the promoter of tumour suppressor genes including Cyclin-dependent kinase inhibitor 2A (CDKN2A, or p16), E-cadherin (CDH1), and Insulin-like growth factor binding protein 1 (IGFBP-1)." (PMID 33086505, 2020). "Similarly, CDKN2A is one of the most frequently inactivated tumor suppressor genes in MPM, deleted in about half of the cases." (PMID 32882916, 2020). "From a practical standpoint, however, deciding whether an individual tumor specimen is “positive for CDKN2A homozygous deletion” for grading purposes requires a defined cutoff value for the percentage of cells with homozygous deletion by FISH." (PMID 33081848, 2020). "This locus encompasses several candidate tumor suppressors, including CDKN2A/B." (PMID 32599735, 2020). "In the present case, immunohistochemical analysis demonstrated overexpression of p16 in both components of the tumor and fluorescence in situ hybridization analysis demonstrated an increased copy number of 9p21 (CDKN2A, p16 gene) in both epithelial and sarcomatous components." (PMID 32005258, 2020). "Additional Cdkn2a loss had no significant impact on tumor formation upon injection in neonatal pups in this model." (PMID 33228790, 2020). "Based on our findings, it is possible that co-administration of inhibitors of MEK, PI3K, mTOR, IDH1, EZH2 or CDK4/6 (to target CDKN2A deletion) may have been effective in slowing or reducing tumour progression." (PMID 33053751, 2020). "CDKN2A is a tumour suppressor that inhibits cell proliferation via various mechanisms." (PMID 33174391, 2020). "An integrated genomic and transcriptomic study of five patient-derived xenografts also determined that the copy numbers of CCND1 and CDKN2A are potential targets of palbociclib and may mediate the suppression of tumor growth." (PMID 33243298, 2020). "The combination synergistically repressed oncogenic MYC and activated the Cdkn2a tumor suppressor." (PMID 32923678, 2020). "As ICB induced a similar immune infiltrate in RT2-cancers and in Stat1- and Cdkn2a-deficient RT2-cancers, the data strongly suggest that senescence induction in the cancer cells was a prerequisite for tumour cell clearance by TH1 cells and IFN-γ-activated type I macrophages." (PMID 32165639, 2020). "This could also explain the finding of CDKN2A monosomy in a primary tumour and disomy (cases 20) or polyploidy (cases 157 and 162) in local recurrences." (PMID 31916407, 2020).
tumor (continued). "A correlation was found for AC but not for SCC, which may be explained by different molecular mechanisms for inactivation of CDKN2A in the two histological tumor types." (PMID 32256975, 2020). "Subsequent comparisons of genomic profiles from an additional twelve LGSC cell models showed frequent deletion of Chr9p (including loss of MTAP and CDKN2A genes) and oncogenic mutations in KRAS and NRAS genes, in agreement with results from previous studies on LGSC tumor tissues." (PMID 30636931, 2019). "Among these genes, CCND1 and MDM2 are known to be oncogenes and CDKN2A is a tumor suppressor." (PMID 30755618, 2019). "However, in the larger TCGA dataset because of the more limited number of histologies, our statistical model accounted for tumor type, and CDKN2A was still a significant marker of poor prognosis." (PMID 31528332, 2019). "Indeed, tumor mutational load, in addition to BRAF and CDKN2A alterations are reportedly similar between patients with complete response and those with rapid progressive disease." (PMID 31426590, 2019). "To assess the accuracy of the information and patterns gleaned from CNVseq, we conducted three separate examinations:A)We examined genome-wide gene expression data from these tumours (DASL HT12.4 array) to compare gene expression in CDKN2A, CDKN2B, MTAP and PTEN.." (PMID 31222134, 2019). "Moreover, CDK2 and SIRT1 expression in the tumor pieces of these patients tended to directly, while CDKN2A inversely, be correlated with GOAT urine levels." (PMID 31766715, 2019). "In addition to the focal deletion region, nearby regions within 9p21.3 also showed high frequency of deletion involving two tumor suppressors (CDKN2A, CDKN2B), MTAP and a cluster of type I IFN genes." (PMID 31311932, 2019). "p16Ink4a/CDKN2A is a tumor suppressor that critically regulates the cell cycle." (PMID 31371816, 2019). "Additionally, the region harboring the cyclin D1 (CCND1) oncogene was amplified and the region harboring the tumor suppressor genes, Cyclin Dependent Kinase Inhibitor 2A (CDKN2A) and CDKN2B, was deleted in both pre- and post-CCRT samples." (PMID 31097034, 2019). "CDKN2A is a gene acting as a tumor suppressor by regulating the cell cycle, therefore, it is reasonable that its abnormal expression pattern would be a common signature in different cancers, and it has been reported as a potential biomarker in previous reports." (PMID 30704464, 2019).